BRCA1 (BRCA1 DNA repair associated)
Diseases named in the same sentence as BRCA1 in open-access papers (continued):
Sharing a sentence is not in itself a finding about the gene and the disease.
breast cancer (continued). "A higher rate of EGFR missense mutations (45.8%) was reported in hereditary BRCA1/2 positive breast tumours, which are typically triple-negative, than in sporadic breast cancers (14.6%)." (PMID 22192147, 2011). "Inheritance of a mutation in the BRCA1 gene confers a 45-65% average lifetime risk for developing breast cancer and an increased risk for developing ovarian cancer." (PMID 21771338, 2011). "For this study, we focused our analysis on a collection of breast cancer samples with BRCA1 mutations." (PMID 22032724, 2011). "What is the best approach to identify the BRCA1 mutation carriers among young women with newly diagnosed breast cancer, in terms of timeliness, sensitivity, specificity?" (PMID 21343941, 2011). "Single-agent cyclophosphamide showed only slight antitumor activity against BRCA1-mutated human breast cancer xenografts growing in nude mice." (PMID 21819606, 2011). "Although this observation has never been described previously, we have shown before that family history of cancer influences a woman's risk of a first primary breast cancer, most notably in women with a BRCA1 mutation." (PMID 21487411, 2011). "A number of studies examining the incidence of breast cancer have reported a lower likelihood amongst BRCA2-mutation carriers compared to BRCA1-mutation carriers." (PMID 22312502, 2011). "Women suffering from breast cancer, showing mutations on the BRCA1 and BRCA2 genes, apparently are more susceptible to present genetic damage in others tissues than healthy individuals." (PMID 21556202, 2011). "In this study, mutations in previously known breast cancer susceptibility genes can explain 13.4% of the analyzed high-risk BRCA1/2-negative HBOC individuals." (PMID 21356067, 2011). "Using this cohort, we estimate the contralateral breast cancer risks in women with a BRCA1 or BRCA2 mutation, and we measure the extent to which host factors, family history, and cancer treatments modify the risk." (PMID 21487411, 2011). "Similar results were found with respect to the reduction of contralateral breast cancer risk in patients with a BRCA1/2 mutation treated with tamoxifen after first diagnosis of breast cancer." (PMID 22312502, 2011). "In our recent report, we described the loss of pRb, coupled with high p16, in BRCA1-defective breast cancers." (PMID 21958427, 2011). "Cell lines, which were generated from mammary tumors growing in genetically engineered BRCA1-deficient mice, demonstrated high sensitivity to doxorubicin in a cell survival assay." (PMID 21819606, 2011). "There are limited studies evaluating breast conservation for BRCA1/2 mutation carriers diagnosed with breast cancer (affected carriers)." (PMID 22295226, 2011). "We demonstrate the use of RNA-Seq to investigate the transcriptomes of BRCA1-mutated breast cancers for gene fusions." (PMID 22032724, 2011). "There is emerging evidence to suggest that BRCA1-linked breast cancer patients treated with chemotherapy regimens containing platinum or doxorubicin and cyclophosphamide have a high likelihood of achieving pathologic complete remission." (PMID 22312502, 2011). "For BRCA1/2 carriers who were diagnosed with breast cancer before the age of 40 years, the cumulative risk of developing contralateral breast cancer after a follow up of 25 years is even higher, i.e. 63%." (PMID 21219598, 2011). "In sporadic breast carcinoma, BRCA1 is rarely mutated, although expression frequently is limited by DNA methylation-induced gene suppression." (PMID 22032251, 2011). "Nevertheless, a low detection rate has also been perceived in another group of families with a single case of female breast cancer (Group E) where the mutation detection rates for BRCA1 and for BRCA2 were 8% and 0%, respectively." (PMID 21232165, 2011). "The age at which first ER+ breast cancers developed was analyzed according to wt BRCA1 allele status." (PMID 21080930, 2010).
breast cancer (continued). "Several recent studies evaluating the prevalence of loss of heterozygosity (LOH) in BRCA1-associated breast cancers have noted that 50 to 90% of these cancers show LOH, with loss of wt BRCA1." (PMID 21080930, 2010). "Of the prevalent breast cancer patients screened for BRCA1 and BRCA2 mutations 519 had tumour pathology information." (PMID 20146796, 2010). "In recent years it has become clear that phenotypic features of a subset of BLBCs resemble those of hereditary BRCA1-mutated breast cancers and are distinctly different from the more common luminal breast tumors." (PMID 21118481, 2010). "Only a small proportion of breast cancer cases can be attributed to mutations in high-penetrance genes such as BRCA1 or BRCA2, and much of the remaining cases are attributed to more common gene variants with lower penetrance." (PMID 21108795, 2010). "The lifetime risk of breast cancer for Caucasian BRCA1 mutation carriers is 60-85%, while the lifetime risk of ovarian cancer is 15-40%." (PMID 20380699, 2010). "We undertook a study to assess the clinical factors that predict for an estrogen receptor positive (ER+) breast cancer in BRCA1 mutation carriers and to characterize the pathologic features of these tumors." (PMID 20149218, 2010). "This is the first study, to our knowledge, that has specifically examined loss of wt BRCA1 in a large cohort of BRCA1-associated breast cancers in relation to ER status." (PMID 21080930, 2010). "In sporadic breast cancers, particularly in ER- cancers, loss of heterozygosity involving large regions of chromosome 17, including the BRCA1 locus, is seen in 49 to 57% of cases." (PMID 21080930, 2010). "We propose that the increased survival associated with a family history of breast cancer, suggesting hereditary breast cancer according to the Modena criteria, should be considered with respect to BRCA1 analysis as a predictor of mutations." (PMID 20219108, 2010). "The Breast and Ovarian Analysis of Disease Incidence and Carrier Estimation Algorithm (BOADICEA) model includes a polygenic component for breast cancer susceptibility in addition to BRCA1/2." (PMID 19904271, 2010). "Mutation of cysteine 61 in the RING finger domain of BRCA1 (BRCA1C61G) has been observed in patients with the familial breast cancer." (PMID 21054854, 2010). "Frequency of lympho-vascular invasion (LVI) in BRCA1 associated breast cancer compared to matched sporadic controls, stratified for tumor type." (PMID 20398395, 2010). "In the present study we investigated the association of these polymorphisms, tagged to genes demonstrated in vitro to be involved in irradiation response, with risk of breast cancer for BRCA1 and BRCA2 mutation carriers." (PMID 21114847, 2010). "Bilateral prophylactic mastectomy has been found to reduce the risk of a future breast cancer for a woman carrying a BRCA1 or BRCA2 mutation by as much as 90%." (PMID 20180951, 2010). "An estimated 5 to 10 percent of all breast cancers are inherited, caused by mutations in the breast cancer susceptibility genes (BRCA1/2)." (PMID 20920338, 2010). "Since the initial study localizing the breast cancer gene BRCA1 to chromosome 17q21 and the isolation of the BRCA1 gene (OMIM#113705), many mutation detection studies have been undertaken." (PMID 20380699, 2010). "In the BRCA1 carrier group, 8 deaths (5 caused by a second tumour arising after breast cancer) and 13 relapses (6 local recurrences and 7 distant recurrences) were reported, whereas in the BRCA negative group 220 deaths and 240 relapses occurred." (PMID 20219108, 2010). "The breast cancer incidence curve in BRCA1 mutation carriers follows closely the shape of the incidence curve for ER-negative disease." (PMID 20482762, 2010). "Accordingly, it has been suggested that BRCA1/2-associated breast cancers progress through the same intermediate steps as sporadic breast cancers, and that DCIS should be considered as a part of the BRCA1/2 tumour spectrum." (PMID 20961453, 2010).
breast cancer (continued). "A number of large studies, facilitated through the Consortium of Investigators of Modifiers of BRCA1/BRCA2 (CIMBA), have evaluated associations between genetic polymorphisms and breast cancer risk in BRCA1 and BRCA2 mutation carriers." (PMID 21114847, 2010). "According to a population-based study from Sweden, 6.8% of breast cancer patients younger than 41 carry mutations in the BRCA1 gene." (PMID 20380699, 2010). "Using a model based approach we estimated that about 24% of the breast cancer FRR to relatives of cases with ER-negative disease is due to BRCA1 mutations." (PMID 20146796, 2010). "The authors subsequently concluded that PBSO was associated with a statistically significant reduction in breast cancer risk amongst BRCA1/2 mutation carriers." (PMID 20961453, 2010). "Rottenberg and colleagues used the genetically engineered BRCA1-deficient breast cancer mouse model to establish AZD2281's efficacy alone and in combination with platinum-based agents." (PMID 20182637, 2010). "Among breast cancer cases unselected for family history (FH), the prevalence of BRCA1/2 mutations is dependent on the population studied and on the age at diagnosis of malignancy." (PMID 20234365, 2010). "Preliminary results from a multicenter, open-label, phase II trial of olaparib in heavily pretreated patients with BRCA1/BRCA2-mutated advanced breast cancer were presented at the American Society of Clinical Oncology in 2009." (PMID 21050422, 2010). "The BRCAPRO model calculates risk of developing breast cancer based on the probability of carrying a BRCA1 or BRCA2 mutation." (PMID 21037853, 2010). "HER2 protein overexpression and/or gene amplification was found in four of the 77 BRCA1-associated breast cancers (one by IHC; three by FISH)." (PMID 21080930, 2010). "Mutation carriers have an increased life-time risk of developing breast cancer of 57% and 40% and of developing ovarian cancer of 40% and 18% for BRCA1 and BRCA2 respectively." (PMID 20398395, 2010). "It is also known that breast cancers in patients with BRCA1 germ-line mutations are more often triple negative than positive for HER2/neu, PR or ER, and the majority of basal-like carcinomas lack ER, PR, and HER2/neu expression." (PMID 21152100, 2010). "The most frequently mutated gene in hereditary breast cancers, BRCA1, is essential for homologous recombination (HR), a fundamental process for maintaining genome stability that permits the reactivation of blocked replication forks." (PMID 21321378, 2010). "Lifetime risks of BRCA1/2 mutation carriers have been estimated at approximately 80% for breast cancer and approximately 40% and approximately 20% for ovarian cancer (BRCA1 and BRCA2, respectively)." (PMID 20920338, 2010). "From this experiment, we selected all of the differently expressed genes associated with the experimental condition "BRCA1-associated breast cancer"." (PMID 20663121, 2010). "Supporting this theory, Hosey and colleagues have shown that transfection of the wild-type BRCA1 gene into HCC1937 cells, an ER- breast cancer cell line homozygous for the BRCA1 mutation, restores ER production." (PMID 20149218, 2010). "Of the 113 most significantly associated SNPs (p<10−3) in our study, three showed significant association (p<0.05) with BRCA1-associated breast cancer risk in a complimentary GWAS." (PMID 21060860, 2010). "The inclusion of phenotypic markers associated with BRCA1 status should improve risk prediction in breast cancer." (PMID 20482762, 2010). "Fewer than 10% of breast cancers are attributable to known mutations in breast cancer susceptibility genes BRCA1 and BRCA2." (PMID 20111735, 2010).
breast cancer (continued). "The BRCAPRO model predicts breast cancer risk on the basis of the probability of carrying a mutation in BRCA1/2, taking cancer status and age of first- and second-degree relatives into account." (PMID 19904271, 2010). "Clinically, breast cancer is believed to begin at an earlier age in BRCA1 and BRCA2 gene mutation carriers compared with sporadic cases." (PMID 20961453, 2010). "Relatively little is known about these BRCA1-associated ER+ breast cancers or about the factors that predict for the ER status of breast cancers that develop in these women." (PMID 20149218, 2010). "ATM deficiency results in lymphoid malignancies and BRCA1 mutation carriers have 50-85% life risk of developing breast cancer." (PMID 20175908, 2010). "The familial breast cancer associated with BRCA1 inactivation develops at younger ages and is frequently bilateral compared to the sporadic types of breast cancer." (PMID 21054854, 2010). "LVI seems to occur as much in BRCA1 germline mutation related breast cancers as in sporadic controls." (PMID 20398395, 2010). "In this study, we found that 81.0% of ER+ BRCA1-associated breast cancers showed LOH with loss of the wt BRCA1 allele." (PMID 21080930, 2010). "The two most important genes that, when bearing a germline mutation, predispose to breast cancer, are the BRCA1 and BRCA2 genes." (PMID 20398395, 2010). "While the loss of BRCA1 has been shown to lead to the development of mammary tumors in mouse models, the genetic diversity within those tumors suggests that the loss of BRCA1 is not directly responsible for tumorigenesis." (PMID 21191148, 2010). "In the case of BRCA1 gene mutation carriers, the cumulative risk of cancer by the age of 70 years ranges between 51% and 95% for breast cancer, and between 22% and 60% for ovarian cancer." (PMID 20961453, 2010). "Pathogenic BRCA1 mutations were identified in 16 women (14%) diagnosed with breast cancer at ⩽30 years of age." (PMID 20234365, 2010). "The mean age at diagnosis of breast cancer in BRCA1 mutation carriers was 42.4 years while in BRCA2 mutation carriers was 34.3 years." (PMID 20579331, 2010). "Germline mutations in the BRCA1 gene predispose to the development of breast cancer, exhibiting a specific histological phenotype." (PMID 20398395, 2010). "Although protection against BRCA1-associated breast cancer and BRCA2-associated gynaecologic cancer was suggested, neither effect reached statistical significance." (PMID 20961453, 2010). "Tneg and basal-like breast cancers represent about 15% of all newly diagnosed breast cancers and preferentially arise in younger women, African-Americans, and BRCA1 mutation carriers." (PMID 20946665, 2010). "These different transcriptional patterns correlate well with critical diagnostic criteria (ER+, PR+, HER-2/neu+, triple negative, BRCA1) that guide both diagnosis and treatment protocols for these types of breast cancers." (PMID 20111735, 2010). "In conclusion, in this study of 77 BRCA1-associated breast cancers, we found similar frequencies of LOH with loss of wt BRCA1 in ER+ and ER- breast cancers." (PMID 21080930, 2010). "Inactivation of 53bp1 suppressed the development of mammary tumors in mice carrying hypomorphic Brca1 mutations (Brca1Δ11/Δ11)." (PMID 21054854, 2010). "The finding that both the NF1 gene and a breast cancer predisposition gene (BRCA1) are located in close proximity on chromosome 17q makes the association of these two conditions intriguing." (PMID 20205809, 2010).
breast cancer (continued). "The contribution of mutations in BRCA1 to the breast cancer FRR for relatives of ER-negative disease and ER-positive disease was estimated to be 24% and 1% respectively." (PMID 20146796, 2010). "As expected, we observed associations with some of the major common genetic variants seen in genome-wide scans of breast cancer in a non-BRCA1/2 mutation background." (PMID 21060860, 2010). "Three patients with BRCA1/2 mutations were sporadic at the time of diagnosis and one patient had only a paternal grandmother with breast cancer aged 65 years." (PMID 20234365, 2010). "A polygenic model is supported, suggesting the joint effect of genes in contributing to breast cancer risk to be rather common in non-BRCA1/2 families." (PMID 20637093, 2010). "We have applied this improved assay for the first time to the detection of truncation mutations in exons 11 of the breast cancer susceptibility genes BRCA1/2 and have evaluated it using 100 clinical genomic DNA test samples." (PMID 20920338, 2010). "The BRCA1 mutation carrier frequency in young breast cancer patients is lower in Estonia than in either Latvia or Russia, which lie just across its border." (PMID 20380699, 2010). "Olaparib (AZD2281) is a novel PARP inhibitor with significant activity in patients with mutation of BRCA1/2 breast cancer, ovarian cancer, or prostate cancer." (PMID 21050422, 2010). "Our data are consistent with those of Foulkes and colleagues who also found an increase in ER+ breast cancers with increasing age among BRCA1 mutation carriers." (PMID 20149218, 2010). "Women with inherited inactivating mutation of BRCA1 gene have about a 65-80% lifetime risk of developing breast cancer." (PMID 21054854, 2010). "Some early work in this area has suggested that one haplotype in BRCA1 is over-represented in individuals carrying deleterious mutations while another haplotype was associated with a 20% increased risk in breast cancer." (PMID 20807450, 2010). "DNA testing for breast cancer susceptibility became an option after the identification of the BRCA1 and BRCA2 genes." (PMID 20579331, 2010). "Intriguingly, the luminal progenitor gene signature shared marked similarity with the basal subtype of breast cancer and preneoplastic breast tissue from BRCA1 mutation carriers." (PMID 20346151, 2010). "Several immunohistochemical and gene expression profiling studies have shown that BRCA1-deficient tumors possess many biological and molecular characteristics of basal-like breast cancer." (PMID 24281106, 2010). "A cohort of 95 women with early-onset breast cancer, diagnosed before age 45, was established and carefully analyzed for mutations in the BRCA1 gene." (PMID 20380699, 2010). "This ability to preferentially target BRCA1-defective cells and spare those with normal function made PARPi an attractive option for the treatment of ovarian and breast cancer patients with BRCA1 germline mutations." (PMID 20182637, 2010).